SHMT1 (serine hydroxymethyltransferase 1)
Description:
Pyridoxal phosphate (PLP)-dependent enzyme that catalyzes the reversible conversion of serine and tetrahydrofolate (THF) to glycine and 5,10-methylene THF, serving as a critical component of the folate cycle and facilitating one-carbon biosynthetic reactions essential for methionine, purine, and pyrimidine synthesis. While its central activity involves serine cleavage, the detailed catalytic mechanisms remain under study, including both retro-aldol cleavage of the PLP-serine C(alpha)-C(beta) bond followed by formaldehyde condensation with THF, and alternative nucleophilic displacement mechanisms of the C(alpha) atom of PLP-serine aldimine involving THF's N5 atom (By similarity). Also catalyzes the cleavage of various 3-hydroxy amino acids, such as L-allo-threonine, L-threonine and 3-phenylserine, forming glycine and the corresponding aldehyde through a retro-aldol process; additionally, it catalyzes the formation of 5-formyltetrahydrofolate from 5,10-methenyltetrahydrofolate. Also functions as a hydroxytrimethyllysine aldolase (HTMLA) catalyzing the second step of the carnitine biosynthesis pathway and exhibits substrate preference with the erythro (S,S) configuration, and more efficiency with L-allo-threonine. In the nucleus, first functions as a lamin-binding scaffold protein that is essential for assembling the de novo thymidylate synthesis complex by co-localizing DHFR and TYMS with the nuclear lamina and anchoring the complex to DNA replication sites. Subsequently, provides one-carbon substrates, specifically (6R)-5,10-methylene-5,6,7,8-tetrahydrofolate, in situ for de novo dTMP synthesis to sustain DNA replication and repair during cell proliferation. Importantly, possesses RNA-binding capability, forming complexes that selectively regulate SHMT2 mRNA translation and dynamically modulate cytosolic and mitochondrial serine and glycine concentrations, thus influencing cellular metabolic status.
Synonyms: SHMT; cSHMT; hcSHMT; MGC15229; MGC24556
Tractability: Small molecule: a structure with a bound ligand is known. PROTAC: ubiquitination databases record sites on it; its protein half-life has been measured.
Target class: Enzyme; Transferase
Safety:
Unwanted effects reported when the protein is acted on. In parentheses: how it was acted on, where the effect was seen, and who reports it.
catalytic activity of TYMS (source: ClinPGx)
Toxic liver disease (source: ClinPGx)
Gene: Protein-coding gene on chromosome 17 (18,327,686 to 18,363,550, reverse strand). Ensembl gene ENSG00000176974.
Subcellular location: Cytoplasm; Nucleus
Subcellular location (Human Protein Atlas): Cytosol; Nucleoplasm
Pathways (Reactome):
Metabolism: Carnitine synthesis; Metabolism of folate and pterines
Gene Ontology:
Molecular function: aldehyde-lyase activity; glycine hydroxymethyltransferase activity; hydroxytrimethyllysine aldolase activity; identical protein binding; L-allo-threonine aldolase activity; lamin binding; mRNA 5'-UTR binding; mRNA regulatory element binding translation repressor activity; protein binding; protein homodimerization activity; pyridoxal phosphate binding; serine binding; small molecule binding; threonine aldolase activity; phenylserine aldolase activity
Biological process: 'de novo' pyrimidine nucleobase biosynthetic process; cellular response to tetrahydrofolate; DNA replication; dTMP biosynthetic process; folic acid metabolic process; glycine metabolic process; L-serine catabolic process; L-serine metabolic process; negative regulation of translation; one-carbon metabolic process; protein homotetramerization; purine nucleobase biosynthetic process; tetrahydrofolate interconversion; tetrahydrofolate metabolic process; carnitine biosynthetic process
Cellular component: cytoplasm; cytosol; extracellular exosome; nucleus; replication fork
Genetic constraint (gnomAD): Loss-of-function variants: 33 observed, 40.96 expected, observed/expected ratio (o/e) 0.81, 90% interval 0.61 to 1.08. The upper end of that interval is the gene's LOEUF score, 1.08, which puts it in group 4 of 6, group 1 being the genes least tolerant of losing a copy. Missense variants: 506 observed, 600.56 expected, observed/expected ratio (o/e) 0.84, 90% interval 0.78 to 0.91. Synonymous variants: 222 observed, 247.09 expected, observed/expected ratio (o/e) 0.9, 90% interval 0.8 to 1.
Homologues: Orthologues: chimpanzee SHMT1 (99% identical), macaque SHMT1 (98% identical), guinea pig SHMT1 (94% identical), rabbit SHMT1 (93% identical), dog SHMT1 (91% identical), mouse Shmt1 (90% identical), rat Shmt1 (90% identical), pig SHMT1 (89% identical), tropical clawed frog shmt1 (80% identical), zebrafish shmt1 (79% identical), Caenorhabditis elegans mel-32 (60% identical), Drosophila melanogaster Shmt (58% identical). Paralogues in human: SHMT2 (63% identical).
Diseases named in the same sentence as SHMT1 in open-access papers:
SHMT1 is named in the same sentence as 99 diseases in open-access papers, as found by Europe PMC text mining. Sharing a sentence is not in itself a finding about the gene and the disease. The quoted sentences say what the papers report.
lung carcinoma (26 papers, 2013 to 2025). "Previous studies demonstrated that SHMT1 was significantly overexpressed in lung cancer tissues, which was associated with increased cell proliferation and tumour progression." (PMID 41154605, 2025). "In lung cancer, SHMT1 and SHMT2 are both highly associated with the infiltration of different types of immune cells, and are potential prognostic biomarkers." (PMID 37147729, 2023). "The upregulation of serine and glycine synthesis has thus been associated with different tumor types, including lung cancer, where expression of the SHMT1 enzyme has been correlated with good prognosis and expression of SMHT2 with poor prognosis." (PMID 31370342, 2019). "SHMT1 polymorphisms have been associated with increased lung cancer risk." (PMID 26717037, 2016). "Although SHMT1 is known to play important roles in several cancers, including lung cancer and HCC, its biological function and clinical relevance in colorectal cancer (CRC) remain poorly understood." (PMID 40738465, 2025). "This suggests that SHMT1 plays a crucial role in maintaining the proliferative capacity of lung cancer cells." (PMID 41154605, 2025). "In lung cancer, SHMT1 indirectly influences mitochondrial SHMT2 expression and helps maintain a balance in the 1-carbon unit flux between the cytoplasm and mitochondria." (PMID 40738465, 2025). "In lung cancer, miR-198 inhibits cell proliferation in vitro and in vivo by directly targeting SHMT1." (PMID 37147729, 2023). "Even with the knockdown of the SHMT1 gene, there was evidence of apoptosis induction in lung cancer." (PMID 35323710, 2022). "For example, compound 2.12, a derivative of the pyrazolopyran scaffold, has a lower dissociation constant when binding to the SHMT1 enzyme-serine complex and is preferred to inhibit SHMT1, eventually leading to cell death in lung cancer cells." (PMID 35531073, 2022). "Pyrazolopyran, an herbicide compound, which was originally shown to inhibit plant SHMT, has been shown to inhibit human SHMT1 and to induce cell death in lung cancer cells." (PMID 36428783, 2022). "Research in lung cancer has indicated that the cell cycle can be arrested owing to a decrease in the expression level of SHMT1." (PMID 33863325, 2021). "SHMT1 knockdown induces apoptosis in lung cancer cells, and SHMT inhibitors block the growth of many human cancer cells." (PMID 33335484, 2020). "Serine hydroxymethyltransferase 1 (SHMT1) is recently found to play critical roles in human cancers including lung cancer, ovarian cancer and intestinal cancer." (PMID 30755243, 2019). "In lung cancer, ovarian cancer and breast cancer, SHMT1 was found to act as onco-protein and promote the progression of these cancers." (PMID 30755243, 2019). "This analysis was focused on UTR2, which (i) is present in the most expressed transcript in lung cancer cells, (ii) shows optimal binding to SHMT1 in vitro and (iii) has an optimal interaction score, as predicted by computational means." (PMID 30809670, 2019). "To test the effect of UTR2 on SHMT1 activity in the cells, we first used the H1299 lung cancer cell line." (PMID 30809670, 2019). "In lung cancer cells, knockdown of SHMT1 induces apoptosis as a result of uracil misincorporation during DNA replication and a decrease in dTMP synthesis." (PMID 30550583, 2018). "On the other hand, we recently demonstrated the crucial role of SHMT1 for the survival of lung cancer cells; albeit being overexpressed also in these cells, SHMT2 appears to play a minor role." (PMID 26717037, 2016). "We recently demonstrated that SHMT1 plays a relevant role in lung cancer, as it is overexpressed in tissue samples from lung cancer patients and NSCLC cell lines." (PMID 26717037, 2016).
lung carcinoma (continued). "Our previously published data demonstrate that, differently from other cancer cell types, lung cancer cells are extremely sensitive to SHMT1 levels." (PMID 26717037, 2016). "Recovery to the same extent (∼about 30%) was also observed after overexpression of SHMT1 in 2.12-treated A549 lung cancer cells." (PMID 26717037, 2016). "Together with lung cancer cell lines A549 and H1299, which over-express both SHMT1 and SHMT2, we also used COLO320 cells that over-express SHMT2 but not SHMT1." (PMID 26717037, 2016). "To validate the ability of 2.12 to inhibit SHMT1 in lung cancer cells, we used gas chromatography/mass spectrometry to evaluate the glycine and serine content in A549 and H1299 cells treated or not with 2.12." (PMID 26717037, 2016). "We previously demonstrated that RNA interference (RNAi) against SHMT1 induces apoptosis in lung cancer cell lines, via the misincorporation and accumulation of uracil in DNA." (PMID 26717037, 2016). "In this paper we show that SHMT1 is overexpressed in tissue samples from lung cancer patients and lung cancer cell lines, suggesting that, in this widespread type of tumor, SHMT1 plays a relevant role." (PMID 25412303, 2014). "The highest levels of SHMT1 expression were found in A549 and H1299; thus these cells were chosen for a more extensive characterization of the role of SHMT1 in lung cancer." (PMID 25412303, 2014). "Our study uncovers an unforeseen role of SHMT1 in lung cancer cells and, more importantly, opens to the possibility to target this protein for the treatment of lung cancer." (PMID 25412303, 2014). "In parallel, the expression of the SHMT1 gene was analyzed in three lung cancer cell lines (H460, H1299 and A549) and an upregulation with respect to a normal lung sample was observed, confirming the trend seen for patients with cancer." (PMID 25412303, 2014). "Folate genes implicated in lung cancer risk include methylenetetrahydrofolate reductase (MTHFR); thymidylate synthase (TYMS); serine hydroxymethyltransferase 1 (SHMT1); and cystathionine β-synthase (CBS)." (PMID 23372658, 2013). "Thus, SHMT1 plays a vital role in nucleotide synthesis, genomic stability, and lung cancer cell proliferation." (PMID 40738465, 2025). "SHMT1 was also reported to be overexpressed in lung cancer cells." (PMID 38460155, 2024). "In addition, miR-218-5p suppresses the cytotoxic effect of natural killer cells by targeting SHMT1 in lung cancer." (PMID 37147729, 2023). "In lung cancer, high SHMT1 expression promotes cell proliferation." (PMID 36699468, 2022). "It has been identified that cytoplasmic SHMT1 is overexpressed in lung cancer." (PMID 35531073, 2022). "Study of lung cancer showed that SHMT1 exerted oncogenic function by regulating cell apoptosis." (PMID 30755243, 2019). "SHMT1 is overexpressed in lung cancer patients and NSCLC cell lines." (PMID 26717037, 2016). "Moreover, administration of 2.12 in A549 and H1299 lung cancer cell lines causes apoptosis at LD50 34 μM and rescue experiments underlined selectivity towards SHMT1." (PMID 26717037, 2016). "In this study we show that in addition to SHMT2, SHMT1 is overexpressed in samples from lung cancer patients and lung cancer cell lines, suggesting that, at least in this type of tumor, SHMT1 might have a relevant role." (PMID 25412303, 2014). "Our data open the possibility to target cytoplasmic SHMT1 to treat lung cancer patients." (PMID 25412303, 2014).
lung carcinoma (continued). "Moreover, cytosolic SHMT1 knockdown increased dUTP incorporation in lung cancer cells." (PMID 38830901, 2024). "We previously showed that SHMT1 knockdown in A549 and H1299 lung cancer cell lines triggered apoptosis and induced a compensatory increase of SHMT2α expression by a yet unknown mechanism, suggesting that SHMT1 might be involved in the regulation of the other isoforms." (PMID 30809670, 2019). "We demonstrated that lung cancer cells are more sensitive to 2.12 when compared to colon cancer cells, and we suggest that this difference could be ascribed, at least in part, to the differential expression of SHMT1 in these cell lines." (PMID 26717037, 2016). "Our data demonstrate that not only SHMT1 targeting may result in more effective outcomes, but more importantly open to the possibility to work on this more easily targetable protein for the treatment of lung cancer patients." (PMID 25412303, 2014). "While both SHMT1 and SHMT2 are overexpressed in lung cancer tissues, their utility as independent prognostic markers remains uncertain, which warrants further validation in a larger cohort." (PMID 41154605, 2025). "Here, we characterized the binding of SHMT1 to the 5′UTR of its mRNA and to three 5′UTRs of SHMT2 isoforms differently expressed in lung cancer, chosen on the basis of their relative abundance in RNA-sequencing data." (PMID 30809670, 2019). "This functional distinction between SHMT1 and SHMT2 suggests that targeting both enzymes could disrupt the metabolic reprogramming driving lung cancer progression." (PMID 40738465, 2025). "Consequently, SHMT1 and SHMT2 coordinate the folate cycle and contribute to cellular proliferation and metabolic demands in specific contexts such as lung cancer." (PMID 40738465, 2025). "In lung cancer cells, SHMT1 inhibition is not due to serine or glycine starvation, indicating different roles of SHMT1 other than the biosynthesis of serine from 3-phosphoglycerate." (PMID 36984785, 2023). "SHMT1 and SHMT2 are up-regulated in patient-derived lung cancer tissue samples." (PMID 30809670, 2019). "SHMT1 and SHMT2 expression levels are cross-related in lung cancer cells; however, the mechanisms by which their expression is controlled to ensure the appropriate amounts of each isoform are unknown." (PMID 30809670, 2019). "Therefore, our findings supported the suggestions that vitamin D may be a therapeutic agent in patients with pulmonary fibrosis and lung cancer, though not only through the regulation of PSAT1 but also the SHMT1 gene." (PMID 38203636, 2023).
breast carcinoma (10 papers, 2009 to 2026). "Fourth, the SHMT1 C1420T polymorphism was associated with decreased risk of breast cancer." (PMID 32340630, 2020). "Sertraline inhibits SHMT1/2 activity and glycine uptake in breast cancer cells to prevent serine accumulation, thereby demonstrating antitumor activity in a serine/glycine synthesis-addicted xenograft breast cancer mouse model." (PMID 39973065, 2025). "In breast cancer cells with LKB1 deficiency, there is an upregulation of PSAT1, PSPH, and serine hydroxymethyltransferase (SHMT1/2), all of which are involved in the de novo serine synthesis pathway (SSP)." (PMID 39973065, 2025). "Tumor PSPH positivity, stromal PSPH positivity, and stromal SHMT-1 negativity are linked to decreased survival in TNBC and HER-2 breast cancers." (PMID 35565690, 2022). "Overexpression of SHMT1 was also identified in lung metastases from breast cancer patients, and SHMT1 was suggested to be a prognostic factor for shorter overall survival for patients with metastatic breast cancer." (PMID 28821754, 2017). "Although high SHMT2, but not SHMT1, was correlated with breast cancer patient mortality, we found that stromal SHMT1 negativity was associated with poor prognosis." (PMID 24979213, 2014). "One breast cancer study found that PHGDH and PSPH are highly expressed in in vitro TNBC, and these, along with SHMT-1, are also elevated in stromal TNBC tumors." (PMID 35565690, 2022). "Appreciably, breast cancer stromal components expressed elevated PSPH, SHMT1, and GLDC levels." (PMID 24979213, 2014). "TMA showed that the TNBC-type breast cancer tissues highly expressed PHGDH, PSPH, and SHMT1, but not the luminal-A-type tissues (p<0.001)." (PMID 24979213, 2014).
lung adenocarcinoma (10 papers, 2016 to 2025). A carcinoma that arises from the lung and is characterized by the presence of malignant glandular epithelial cells. "Studies on lung adenocarcinoma have shown that miR-218-5p reduces the cytotoxic activity of natural killer cells against lung adenocarcinoma cells by targeting SHMT1." (PMID 40427537, 2025). "In this study, we found that the proliferation of lung adenocarcinoma cells was more strongly dependent on SHMT2 than on SHMT1." (PMID 38460155, 2024). "MicroRNA-198 can downregulate SHMT1 expression to suppress the proliferation of lung adenocarcinoma cells, which shows a more effective alteration than silencing SHMT1 with siRNA." (PMID 35531073, 2022). "MiR-218-5p and miR-24-3p have also been reported to suppress the NK killing effect in CRC by targeting paxillin (PXN) and in lung adenocarcinoma by targeting Serine Hydroxymethyltransferase 1 (SHMT1), respectively." (PMID 36189271, 2022). "Yang and collaborators reported that miR-218-5p suppresses the NK-mediated killing of lung adenocarcinoma by targeting Serine Hydroxymethyltransferase 1 (SHMT1)." (PMID 32161759, 2020). "Moreover, the protein expression levels of Fasn, Shmt1, Arg1, and Hk2, that have important functions in cell proliferation and growth, were studied by Western blot analysis and these experiments confirmed their up-regulation in lung adenocarcinomas." (PMID 27602772, 2016). "We measured the protein expression of SHMT1 and SHMT2 in lung adenocarcinoma cells and human bronchial epithelial cells (BEAS‐2B)." (PMID 38460155, 2024). "We clarified that the inhibitory effect of SHIN1 on lung adenocarcinoma cells was mediated mainly by SHMT2 but not by SHMT1." (PMID 38460155, 2024). "Notably, microRNA-218-5p inhibits SHMT1 to suppress the natural killer (NK) cells and exerts a negative effect on lung adenocarcinoma." (PMID 35531073, 2022).